OR4K5 (olfactory receptor family 4 subfamily K member 5)
Description:
Odorant receptor.
Synonyms: OR14-16
Tractability: Small molecule: it belongs to a druggable protein family. Antibody: UniProt places it where antibodies can reach, with medium confidence; UniProt predicts a signal peptide or a membrane-spanning region; its Gene Ontology location is reachable by antibodies, with medium confidence.
Gene: Protein-coding gene on chromosome 14 (19,920,607 to 19,921,578, forward strand). Ensembl gene ENSG00000176281.
Subcellular location: Cell membrane
Pathways (Reactome):
Sensory Perception: Expression and translocation of olfactory receptors
Gene Ontology:
Molecular function: olfactory receptor activity; G protein-coupled receptor activity
Biological process: detection of chemical stimulus involved in sensory perception of smell; G protein-coupled receptor signaling pathway
Cellular component: plasma membrane; membrane
Genetic constraint (gnomAD): Loss-of-function variants: 1 observed, 0.48 expected, observed/expected ratio (o/e) 2.09. That is too few expected variants to judge how well the gene tolerates losing a copy. Missense variants: 520 observed, 392.07 expected, observed/expected ratio (o/e) 1.33, 90% interval 1.23 to 1.43. Synonymous variants: 187 observed, 147.09 expected, observed/expected ratio (o/e) 1.27, 90% interval 1.13 to 1.43.
Homologues: Orthologues: macaque OR4K5 (92% identical), rabbit OR4K5 (85% identical), dog OR4K5 (83% identical), mouse Or4k5 (82% identical), rat Or4k5 (81% identical). Paralogues in human: OR4K15 (67% identical), OR4K14 (59% identical), OR4K1 (58% identical), OR4K17 (58% identical), OR4K13 (56% identical), OR4F6 (54% identical), OR4K2 (54% identical), OR4F5 (53% identical), OR4F4 (52% identical), OR4L1 (52% identical), OR4F15 (52% identical), OR4F17 (52% identical), and 116 more.
Diseases named in the same sentence as OR4K5 in open-access papers:
OR4K5 is named in the same sentence as 1 disease in open-access papers, as found by Europe PMC text mining. Sharing a sentence is not in itself a finding about the gene and the disease.
OR4K5 shares sentences with these, for which no sentence is quoted: bipolar disorder (1 paper).